CXCL10 (C-X-C motif chemokine ligand 10)
Diseases named in the same sentence as CXCL10 in open-access papers (continued):
Sharing a sentence is not in itself a finding about the gene and the disease.
tumor (continued). "Cluster 10 expressed high levels of Cxcl9 and Cxcl10, which encode for the eponymous chemokines that are important for the recruitment and spatial localisation of CD8+ T cells in tumours." (PMID 40745918, 2025). "Meanwhile, EZH2 inhibition enhanced natural killer cell-mediated tumor growth inhibition by re-expressing C-X-C motif chemokine ligand 10 and enhancing natural killer cell migration and recruitment to tumor sites." (PMID 40028035, 2025). "Previous studies have reported that CXCL10/CXCR3 signaling is required for T cell tumor infiltration and tumor immunotherapy." (PMID 40315321, 2025). "Because high circulating CXCL10 functions as a systemic decoy that redirects anti-tumor immune cells away from the primary site, a complementary therapeutic approach is the systemic neutralization of this chemokine using monoclonal antibodies (mAb)." (PMID 41516196, 2025). "This activation leads to IRF3 phosphorylation and production of type I interferons (e.g., IFN-β) and inflammatory cytokines (e.g., CXCL10, IL-6), enhancing the tumor’s immune profile." (PMID 39949780, 2025). "Cell death can also stimulate type 1 interferon (IFN) secretion by tumor cells via Toll-like receptor 3 (TLR3), which leads to production of the chemokine CXCL10, which has been linked to cancer development and progression." (PMID 41149451, 2025). "CXCL10, a chemokine, plays a ‎dual role in cancer by attracting immune cells such as T cells, NK ‎cells and macrophages to ‎the tumor site." (PMID 40760734, 2025). "While immunosuppressive factors such as CCL2, CXCL12, IL-4, and IL-10 sustain an immune-excluded TME, pro-inflammatory mediators like IFN-γ, TNF-α, and CXCL10 counteract these effects by promoting immune cell infiltration and tumor suppression." (PMID 40330466, 2025). "To summarize our findings concisely: we have uncovered a novel mechanism through which PRMT5 promotes tumor growth, namely by regulating CXCL10 expression within tumor cells while facilitating recruitment of T cells via interaction between CXCL10 and CXCR3." (PMID 41463372, 2025). "Women with high CXCL10 tumor expression had a better prognosis compared to those with lower CXCL10 expression levels." (PMID 41463176, 2025). "Their study elucidates that LDRT recruits stem cell-like progenitor exhausted CD8+ T cells (CD8+ Tpex) from draining lymph nodes to the tumor site via the CXCL10/CXCR3 axis, enhancing the sensitivity of tumors to DPVB and achieving tumor regression." (PMID 40317077, 2025). "In the view of personalized treatment paradigms, CXCL10-targeted strategies promise to transform cancer immunotherapy by reprogramming the tumor microenvironment, overcoming resistance and achieving durable clinical responses." (PMID 40760734, 2025). "The combination of XVir-N-31 and ribociclib was shown to induce an increase in the M1/M2 ratio, which was primarily driven by upregulation of CXCL10 in vivo tumor xenograft models." (PMID 41463246, 2025). "Oncolytic adenovirus carrying CXCL10 significantly inhibits tumor growth and prolongs survival by continuously secreting CXCL10 and recruiting CD8+ T cells and NK cells expressing CXCR3 to the core tumor area." (PMID 41425703, 2025). "Effector T cells primed in the spleen by the combination therapy migrates to the tumor site via chemokine‐guided trafficking mechanisms involving CXCR3 and CXCL10 in the tumor microenvironment." (PMID 40498983, 2025). "Mechanistically, CXCL10 plays a key role by recruiting CXCR3+ CD8+ T cells to the tumor microenvironment, which in turn enhances IFN-γ production and sustains a Th1‐polarized immune response." (PMID 40760734, 2025). "From snRNA-seq global clustering, Cxcl10+ and Cxcl9+ cells were enriched in a subset of the tumor cluster and an adjacent subset of luminal AV cluster in the young." (PMID 41332581, 2025).
tumor (continued). "CXCL10 is produced by a variety of cells in the tumor microenvironment, including ‎tumor cells, ‎stromal cells, endothelial cells, and infiltrating immune cells such as ‎macrophages and dendritic cells." (PMID 40760734, 2025). "The results demonstrated significantly higher mRNA expression of IFN-γ, TNF-α, IL-2, IL-12a, CXCL9, and CXCL10 in the tumor tissue of the PD-L1-KO/ZG16 overexpression group compared to the control group." (PMID 39958358, 2025). "CXCL10-expressing tumours displayed significantly elevated CXCL10 serum concentrations both before CAR T cell infusion and at the study endpoint." (PMID 41366257, 2025). "Elevated levels of CXCL9, CXCL10, and CXCL11 in ascitic fluid facilitate NK cell trafficking to tumor sites and are associated with impaired tumor progression." (PMID 41567203, 2025). "This suppression reduces the intratumoral levels of chemokines such as CXCL9 and CXCL10, thereby impairing Teff recruitment and infiltration into the tumor site 54-55." (PMID 40303336, 2025). "Four animals were excluded from the primary analysis (two CXCL10, two unmodified) due to signs of pre-infusion GvHD (n = 3) or ectopic tumour localisation in the ovary (n = 1)." (PMID 41366257, 2025). "Poor tumor infiltration by T cells has been attributed to potent epigenetic silencing of the genes encoding the Th1-type chemokines CXCL-9 and CXCL-10 in tumors." (PMID 39996769, 2025). "Autocrine signaling of the Cxcl10/Cxcr3 axis was shown to promote tumor cell growth, motility, and metastasis." (PMID 40486289, 2025). "The results revealed that PRMT5 deficiency led to elevated expression levels of CXCL10, which plays a crucial role in attracting CD8+ T cells to the tumor site." (PMID 41463372, 2025). "A disconnect between high CXCL10 expression and low T-cell density in the primary tumor, contrasted with high T-cell accumulation in CXCL10-rich pulmonary niches, would provide strong correlative evidence for the decoy mechanism." (PMID 41516196, 2025). "When circulating CXCL10 concentrations surpass those within the primary tumor, a systemic chemokine gradient is established, serving as an immune decoy that intercepts CXCR3-A+-expressing effector cells." (PMID 41516196, 2025). "In contrast to strategies aimed at inhibiting CXCL10’s pro-tumor effects, a second major therapeutic paradigm is to harness its potent immune-recruiting capabilities." (PMID 41516196, 2025). "Inflammatory cytokines (such as CXCL9 and CXCL10) induced by nCRT can also attract CD8+ T cells to the tumor site, enhancing their cytotoxic effect." (PMID 40936903, 2025). "Clinically, modulation of CXCL10 signaling offers a promising approach to reprogram the tumor microenvironment." (PMID 40760734, 2025). "As previously acknowledged, CCL5 and CXCL10 serve as crucial signaling bridges between NK cells, T cells, and tumor cells." (PMID 40678068, 2025). "CRTC1 knockdown potentiated the therapeutic efficacy of atezolizumab, evidenced by xenograft tumor regression, increased CXCL10/11 expression, and elevated serum concentrations of IFN-γ and IL-2." (PMID 40977688, 2025). "Mechanistically, the loss of PML increases STAT1 binding to the CXCL10 promoter, likely associated with a PML-regulated region on the promoter, thus upregulating CXCL10 expression in tumor cells and aiding the infiltration of immune cells." (PMID 40909948, 2025). "The relative RNA expression demonstrated that Ccl5, Ccl8, Cxcl9, Cxcl10, Cxcl13 and Ccl21 were significantly higher in the 4MOSC1 tumours following oHSV therapy." (PMID 39219056, 2025). "For example, CXCL1 and CXCL2 promote angiogenesis, whereas CXCL9 and CXCL10 exhibit angiostatic effects, which can influence the tumor's vascularization and growth." (PMID 40242222, 2025). "In this study, we showed that inflammatory monocytes, which in human tumours correspond to CXCL9+CXCL10+ macrophages, drive T cell restimulation in the TME." (PMID 39604727, 2025).
tumor (continued). "These cells mount rapid responses upon antigen re‐exposure and secrete chemokines such as CXCL10, which attract additional anti‐tumor immune cells, including NK cells, to the tumor site." (PMID 40922069, 2025). "By facilitating ‎the ‎infiltration of immune cells into the tumor microenvironment, CXCL10 not only impairs ‎tumor ‎growth and metastasis, but also disrupts angiogenesis, which is essential for the ‎blood supply and ‎spread of the tumor." (PMID 40760734, 2025). "Butyrate has been reported to exert immunomodulatory effects and activate antitumor immunity by increasing MHC-I levels in tumor cells and inducing CXCL10 secretion, leading to CD8 + T cell recruitment, which were also confirmed in the present study." (PMID 41410712, 2025). "Chronic P.g. infection increases IL-6 secretion via TLR signaling, which activates STAT1 and STAT3, driving tumor progression through a feedback loop involving CXCL10, PD-L1, and GAS6 genes." (PMID 40924302, 2025). "Gene expression analyses in tumor tissues showed significantly increased mRNA levels of Cxcl10 and Cdkn1a in the combination treatment group, in line with the in vitro responses to CM272 in cultured PDAC cells." (PMID 39810240, 2025). "Considering the crucial involvement of the CXCL10 pathway in tumor progression, an analysis of data from the TCGA cohort revealed a positive relationship between CXCL10 expression levels and immune cell infiltration." (PMID 41463372, 2025). "By contrast, M1 macrophages, though less well classified and capable of subtype interconversion, dominate early tumor stages, releasing TNF-α, CXCL9, CXCL10, iNOS, and ROS to induce inflammation and eliminate tumor cells." (PMID 40948759, 2025). "The IFN-γ signaling pathway, activated by T cells and NK cells, induces CXCL9 and CXCL10 expression in tumor and stromal cells." (PMID 40475782, 2025). "CXCL10-expressing tumours demonstrated significantly slower growth kinetics, higher tumour control rates at day 14 (88% vs. 29%, p = 0.04), and prolonged median event-free survival (49 vs. 21 days; p = 0.0009; HR = 4.7, 95% CI 1.2–17.9) compared with controls." (PMID 41366257, 2025). "Locally, within the primary tumor, CXCL10 can exert potent anti-tumor effects by recruiting cytotoxic T cells and NK cells, consistent with its favorable prognostic value when confined to the TME." (PMID 41516196, 2025). "Epigenetic reprogramming can sensitize cancer cells to immune checkpoints blocking therapies through the upregulation of immunostimulatory cytokines (e.g. CXCL9 and CXCL10) that recruit T lymphocytes to the tumor site." (PMID 40317004, 2025). "CAR T cell recruitment and tumour control in vivo was enhanced through CXCL10 expression by engineered tumour cells." (PMID 41366257, 2025). "This spatial gene-expression pattern mirrors our observation that CXCL10-high tumors harbor the highest fold-change in CTL density within tumor cell nests." (PMID 40497965, 2025). "CXCL10 plays a multifaceted and context-dependent role in cancer progression, functioning both as a mediator of anti-tumor immunity and, paradoxically, as a promoter of immune evasion and metastasis." (PMID 40760734, 2025). "CXCL10’s anti-tumor effects extend beyond attracting adaptive immune cells; it also influences the polarization of TAM." (PMID 41516196, 2025). "These proteases not only degrade the extracellular matrix to facilitate tumor invasion but can also cleave immune checkpoint molecules (such as PD-L1, programmed death ligand 1) or chemokines (such as CXCL10, c-x-c motif chemokine ligand 10) in the TME." (PMID 41451209, 2025). "Results showed that upon cytokine stimulation most of the studied genes were expressed at a lower level in the tumor cells than in control cells, such as Stat1, Irf1, Cxcl9, Cxcl10, IκBα, and Bcl2 (p< 0.05)." (PMID 40287766, 2025). "The role of CXCL10 is to recruit immunosuppressive cells (such as Treg cells) to the tumor, and these cells suppress the activity of effector T cells." (PMID 41376630, 2025).
tumor (continued). "The TRIB3/STAT1/CXCL10 axis modulated the infiltration abundance of CD 8+ T cells in tumor tissues, leading to the immune escape phenomenon." (PMID 38604154, 2024). "At the same time, it promoted the secretion of CXCL9 and CXCL10 to recruit NK cells to the tumor, killing tumor cells." (PMID 38347129, 2024). "The results suggest that the prostate has a unique environment that promotes local CXCL10 synthesis, which is crucial for attracting CXCR3+ effector cells to tumor-associated TLO." (PMID 38745115, 2024). "In vitro, both pharmacological inhibition and genetic targeting of VPS34 enhance cGAS-STING-mediated expression and secretion of CCL5 and CXCL10 across various tumor cell types." (PMID 40395527, 2024). "Some tumor treatments to induce CXCL9 and CXCL10 expression in tumor cells also potentially benefit tumor immunotherapeutic efficacy when administered by a combination strategy." (PMID 38953994, 2024). "At the level of tumor-infiltrating leukocytes, MH treatment led to a small (1.6-fold) but insignificant increase in the expression level of the chemokine CXCL10." (PMID 38444857, 2024). "Only the administration of CXCL10-Fc to mice transferred with CXCR3+ CD8+ T cells led to a significant decrease in tumor size." (PMID 39474427, 2024). "In studies involving Burkitt’s lymphoma in nude mice, CXCL9 and CXCL10 have been reported to induce tumor necrosis." (PMID 39409924, 2024). "The C-X-C motif chemokine ligand 9 (CXCL9) and CXCL10, which are interferon γ (IFN-γ)-inducible chemokines, are predominantly secreted by tumor-residing CD103+ dendritic cells (DCs) and tumor-associated macrophages." (PMID 38518770, 2024). "To achieve this, we measured the levels of chemokines (CCL5, CXCL9, and CXCL10) in tumor tissues using ELISA across different treatment groups." (PMID 38931345, 2024). "Immune Response and Prognosis: CXCL9, CXCL10, and CXCL13 are linked to favorable prognosis due to their role in enhancing the immune response at the tumor site, suggesting their potential as biomarkers for immune contexture in cancer." (PMID 39546375, 2024). "IFNα specifically mediated CXCL10 expression in both tumor cells and PBMCs to recruit and activate CD8+ T cells, which expresses CXCR3 abundantly." (PMID 38953994, 2024). "Analysis of tumor-associated RNA revealed high JAK2, PD-L1, CCL2, and CXCL10 expression in ALKBH5-overexpressing mice compared to wild-type mice." (PMID 38872221, 2024). "CXCL10 is related to a wide range of human diseases, consisting of immunodeficiency, infectious diseases, chronic inflammation, tumor growth, metastasis, and dissemination." (PMID 39359425, 2024). "Evidence shows a significant connection of the CXCL10 expression to the development of tumors, signature of tumor microenvironment, infiltration of immune cells, alterations of genetics, and the prognosis of the patient." (PMID 39443817, 2024). "CXCL10 plays multiple roles in regulation of the immune response and the tumor development by participating the interactive processes of immune and cancer cells." (PMID 39443817, 2024). "The stromal predilection appears to be driven by low tumor cell MHC class II (HLA-DR), CXCL9, and CXCL10 expression as increased tumor cell expression of these correlated with significant increases in parenchymal T cell infiltration." (PMID 38822345, 2024). "How significant is the direct effect of CXCL10-Fc on the ability of CXCR3+ CD8+ T cells to limit tumor growth?" (PMID 39474427, 2024). "There is increasing evidence that CXCL10 exhibits tumor-promoting abilities in many types of human cancer." (PMID 39268223, 2024). "In estrogen receptor-positive breast tumors, CXCL10 inhibits vascular endothelial growth factor levels to reduce tumor burden." (PMID 38957317, 2024). "Particularly, we found that CD8+ T lymphocytes abundantly expressed CXCR3, a receptor of CXCL10, by flow cytometry, indicating that tumor-intrinsic CXCL10 potentially recruited CD8+ T in tumor microenvironment." (PMID 38953994, 2024).
tumor (continued). "CXCL10, a chemokine known for its role in immune cell trafficking, and shown to be upregulated in the tumor following VSV-NDV treatment, has significant beneficial effects in the TME, particularly in enhancing CD8+ T cell responses." (PMID 39410025, 2024). "These modified MSCs recruit and activate natural killer (NK) cells and macrophages, boosting interferon-gamma (IFN-γ) and CXCL10 levels in the tumor microenvironment." (PMID 39796040, 2024). "Huang and colleagues (2020) found a strong positive correlation between the gene expression of CXCL10 and the infiltration into the tumor of immune cells (B cells, CD8+ T cells, CD4+ T cells, macrophages, neutrophils, dendritic cells)." (PMID 39339213, 2024). "Particularly, we identified a novel subset, CXCL10+ conventional dendritic cells (cDCs), which are abundant in triple-negative breast cancer (TNBC) and have the ability to recruit tumor-associated macrophages (TAMs)." (PMID 39104420, 2024). "To assess the effects of CXCL10 on anti-tumor immunity, we examined the effects of CXCL10 on the production of cytotoxic proteins and effector cytokines in mouse CD8+ T cells." (PMID 39346534, 2024). "Further strengthening these data, immunohistochemical and immunofluorescent analysis revealed an overall significant increase in the levels of CXCL9 and CXCL10 within the TME of mouse PDAC tumours upon IGF blockade." (PMID 39165364, 2024). "During early EGFR-TKI treatment, increased CXCL10 levels stimulated oncogenic signaling in persisting tumor cells, contributing to EGFR-TKI resistance through autocrine and paracrine pathways." (PMID 39114657, 2024). "Further research is needed to unravel the interplay between the CXCR3/CXCL10 axis, the metastatic niche as well as the tumour cell." (PMID 39146303, 2024). "Studies have shown that autophagy enhances the secretion of chemokines, such as CXCL10, by tumor cells, attracting effector T cells and NK cells to tumor sites." (PMID 39840028, 2024). "CXCL9 and CXCL10 (CXCL9/10) signal through C-X-C motif chemokine receptor 3 (CXCR3) to promote the tumor infiltration of CXCR3+ effector T cells, including type 1 T helper (Th1) cells and CD8+ cytotoxic T lymphocytes." (PMID 38518770, 2024). "CXCL9 and CXCL10 expression have been reported to contribute to the generation of a "hot" tumor microenvironment." (PMID 38226288, 2024). "CXCL10 (IP-10) and CCL2 (MCP-1) were both found to have significant associations with higher tumor burden in the E0771 ICI monotherapy study and the combined E0771 and 4T1 groups treated with anti-PD-1." (PMID 39623404, 2024). "In the tumour microenvironment, CCL5 plays a crucial role in recruiting dendritic cells that predominantly present antigens to CD8+ T cells, and CXCL10 enhances the infiltration of CD8+ T cells into tumours." (PMID 38796460, 2024). "Chemokines chemokine C-C motif ligand (CCL) 9 (CCL9), CCL17, CCL20, CXCL5, CXCL9, and CXCL10 secreted by hepatocytes regulated tumor progression by acting on CD8+ T cells." (PMID 39346534, 2024). "Irradiation stimulates tumor cells to release chemokines (CXCL16 and CXCL10) that activate T cells and increase their recruitment into the tumor." (PMID 39199577, 2024). "We thus demonstrated a possible interaction of CXCR3 expressed by activated T cells and CXCL10 secreted by tumor cells." (PMID 38495500, 2024). "In response to type I IFN exposure, NK cells produce chemo-attractants such as chemokine (C-X-C motif), ligand (CXCL) 9, and CXCL10, influencing attraction to the tumor microenvironment of innate immunity-related cells [Wennerberg 2015]." (PMID 38256021, 2024). "Regarding the underlying mechanism of the activation of tumor-infiltrating T cells, we observed that OBP-702 increased the release of CCL5 and CXCL10 from murine NHOS cells more strongly than OBP-301." (PMID 39108499, 2024). "Meanwhile, Cxcl10 has inhibitory effect on tumor progression, Cxcl12, Cxcl14, Ppbp, Pf4 and Ccl8 play an important role in promoting tumor progression." (PMID 38622609, 2024).